MCL1 (MCL1 apoptosis regulator, BCL2 family member)
Diseases named in the same sentence as MCL1 in open-access papers (continued):
Sharing a sentence is not in itself a finding about the gene and the disease.
tumor (continued). "It is thus evident that Mcl-1 confers tumor cells with resistance against not only conventional therapies but also targeted therapies, contributing to poor clinical outcomes." (PMID 36045907, 2022). "Deficiency of 14-3-3ζ upregulated BAD and BIM and decreased MCL-1 to increase BAX, cleaved caspase 7, and cleaved caspase 3 toward tumor cell anoikis." (PMID 36230714, 2022). "Such regions are presumed to contain genes critical for tumor cell proliferation and survival; in this case, genes such as MCL1, BCL9, CKS1B, and ILF2, and members of the ubiquitin-proteasome pathway are found in the affected regions." (PMID 35912171, 2022). "Our data showed that this combination with a Mcl‐1 inhibitor re‐sensitized FBW7‐null tumours to JQ1 treatment." (PMID 35132755, 2022). "A novel small‐molecule, BI‐44, was developed, which effectively suppressed BMI1/MCL1 expressions and inhibited tumour formation and progression in preclinical models." (PMID 35794816, 2022). "While in some models BH3 mimetics antagonizing MCL-1 efficiently counter tumor progression, the sole targeting of MCL-1 in solid tumors proved little efficiency to trigger cell death on its own, both in xenograft and PDX immunodeficient mice models." (PMID 36104324, 2022). "Using quantitative Bcl-2 protein profiles of BAK, BAX, BCL2, BCL(X)L, and MCL1 as model input for DR_MOMP, we were able to calculate the sensitivity of individual tumor cells to the process of mitochondrial apoptosis initiation." (PMID 34754079, 2022). "MCL-1 inhibition with S63845 led to a significant impairment of tumour growth with reduction in post-treatment tumour weight to around one third when compared to vehicle treated controls (mean of 636 mg down to 184 mg, P = 0.0112)." (PMID 33785871, 2021). "The results showed that circMTO1 facilitated human granulosa-like tumor cell behavior by regulating MCL1 expression via miR-320b." (PMID 34413875, 2021). "We show that MCL-1 is essential in established tumours with genetic deletion inducing tumour regression and inhibition with the MCL-1-specific BH3-mimetic drug S63845 significantly impeding tumour growth." (PMID 33785871, 2021). "Several anti-apoptotic proteins, such as Survivin and members of the Bcl family (Bcl-XL, Bcl-2, and Mcl-1), which are essential for tumor cell survival, are direct target genes of STAT3 and downregulated as a consequence of STAT3 inhibition." (PMID 34638708, 2021). "Preclinical data suggest synergistic anti-tumor effect of PV and venetoclax (inhibitor of anti-apoptotic Bcl-2 protein) when PV promotes MCL-1 (myeloid leukemia cell 1) degradation, a known mechanism of resistance to venetoclax (Ven)." (PMID 34768899, 2021). "The apoptosis-associated protein expression in the tumor section was examined by immunohistochemical analysis, and the results showed that TET treatment reduced the levels of c-FLIP, MCL-1, and XIAP but increased the signals of cleaved-caspase-3, -8, and -9." (PMID 34885686, 2021). "IHC staining revealed that MCL1 expression was higher in RCB-1130 tumor xenografts in HFD-fed mice compared with those in normal diet–fed mice." (PMID 34156978, 2021). "A treated tumor and a skin metastasis sample were obtained in the 16th month, and both showed MCL1, TERT, and MDM4 amplifications." (PMID 34680239, 2021). "To further evaluate the in vivo anti-tumor activity of MCL-1 inhibitors for PEL, we utilized NOD/SCID xenograft mice injected intraperitoneally with BCBL-1 cells." (PMID 33471866, 2021). "Together these results reveal that MCL-1 is an essential gene in established tumours and that targeting MCL-1 at clinically actionable stages of tumour development can result in tumour regression with long-term impact on survival." (PMID 33785871, 2021). "In previous study, myeloid cell leukemia-1 (MCL-1) is an anti-apoptotic protein and was reported in tumor progression." (PMID 34312371, 2021).
tumor (continued). "Consistently, studying a panel of tumour tissue specimens on a tissue microarray revealed that high expression of MCL1 predicts poor outcome in BC in all but the HER2 amplified subtype." (PMID 34903710, 2021). "The treated tumor showed several CNVs in driver genes, including amplifications in MCL1, TERT, CCND1, AKT1, MYC, EGFR, and FGFR3; deletions in CDK1B, CDKN2A and CDKN2B; a PIK3CA hotspot mutation; and a high TMB." (PMID 34680239, 2021). "The antiapoptotic protein Mcl-1 is expressed in various types of malignancies, and Mcl-1 is important for the proliferation, differentiation, and survival of tumor cells because it modulates the apoptosis pathway." (PMID 34781999, 2021). "Several MCL-1 inhibitor trials are underway, with promising preclinical data demonstrating in vitro tumor cell death and in vivo tumor growth inhibition." (PMID 34301270, 2021). "By analysing several protein markers altered by SD‐36, we detected significantly reduced levels of STAT3 and Mcl‐1 in the SD‐36‐treated U251 tumours." (PMID 34291563, 2021). "This causes, in the downregulation of antiapoptotic protein, BCL-2, and cleavage of MCL-1 suppressing tumor growth." (PMID 33804548, 2021). "MiR-15a-5p is a tumor suppressor, promoting apoptosis and inhibiting cell proliferation by targeting multiple oncogenes, including Bcl-2, Mcl1, CcnD1, and Wnt3A33,34." (PMID 33456354, 2021). "Cell models were constructed by transfecting OE-NC, OE-circMTO1, OE-circMTO1 + si-NC, and OE-circMTO1 + si-MCL1 into human granulosa-like tumor cells to elucidate the role of the circMTO1/miR-320b/MCL1 axis." (PMID 34413875, 2021). "This tumour-repressive effect of Mcl1 deletion was sustained and median survival increased from 47 to 91 days (P = 0.0022) relative to WT controls with 4/9 recipients of Mcl1fl/fl tumours surviving long term with no palpable tumour remaining." (PMID 33785871, 2021). "MS1 induces apoptosis in a variety of MCL-1-dependent tumor cells with higher sensitivity than NoxaA." (PMID 33883020, 2021). "Mcl-1 plays a critical role as a pro-survival factor, as well as a pro-proliferative factor, in many tumour types." (PMID 33627786, 2021). "USP9X has been shown to promote Mcl-1 stabilization and to increase tumor cell survival in response to radiation and chemotherapy in several tumor types." (PMID 34277417, 2021). "The primary treatment-naïve tumor was extracted in the diagnosis and had MCL1 and NOTCH3 amplifications, and a BRCA1 deletion." (PMID 34680239, 2021). "Overexpression of MCL1 is a distinctive mitochondrial adaptation found in respiratory tumorigenesis, a state of tumor growth with preserved cellular respiration." (PMID 34831420, 2021). "Anti-apoptosis- and proliferation-related proteins, such as CyclinD1, XIAP, C-FLIP, and MCL-1, were all decreased in the tumor tissues in the combination group." (PMID 33922992, 2021). "Through the formation of a "target protein-PROTAC-E3 ligase" complex, the affinity between MCL-1 and the E3 ligase CRBN is effectively enhanced, which selectively degrades MCL-1 to obtain stronger tumor cell killing activity." (PMID 33883020, 2021). "In contrast, Pin‐1 deficiency leads to FBXW7 overexpression that subsequently limits MCL‐1 expression, thereby sensitizing the tumor cells to drugs like Taxol." (PMID 33822486, 2021). "Collectively, this suggest that Mcl-1 is critical for both the initiation and progression of tumor in Eμ-Myc mice." (PMID 34336857, 2021). "More recently, a highly specific MCL1 inhibitor, S63845, was shown to have potent anti-tumour activity as a single-agent in preclinical leukaemia models, as well as in combination with ABT-199 in BC PDX studies." (PMID 34903710, 2021).
tumor (continued). "We therefore investigated the ability of MCL-1 deletion to suppress MMTV-PyMT tumour growth when the downstream apoptotic effectors BAX/BAK were reduced." (PMID 33785871, 2021). "In this study, we found that Oct4 regulates Stat1 expression, which leads to cell survival via enhanced Mcl-1 expression and promotes tumor growth in a Stat1-dependent manner." (PMID 34685622, 2021). "Analysis of a receiver operating characteristic curve (area under curve = 0.6785) showed that the expression of MCL-1 is an important critical value for predicting prognosis in 30.0% of the NSCLC tumor cell types." (PMID 34178945, 2021). "In keeping with previous results, the pSTAT3/CEBPD/MCL1 axis was upregulated in the HFD-fed tumor xenografts." (PMID 34156978, 2021). "Since LANA, a master regulator of KSHV latency, is highly expressed in all latently infected tumor cells, we examined the relative expression levels of MCL-1 in KSHV-positive PEL cell lines compared to a KSHV-negative cell line." (PMID 33471866, 2021). "Numerous genetic mouse models have been developed to address the role of Mcl-1 in tumor initiation and progression." (PMID 34336857, 2021). "In tumor models, HIF1α can directly impact apoptosis by upregulating the pro-survival gene myeloid cell leukemia sequence-1 (Mcl-1)." (PMID 34396954, 2021). "Mice with Mcl-1 deletion displayed improved survival, with 30% of these mice experiencing tumor regression." (PMID 34336857, 2021). "In MM, however, BH3 profiling has revealed tumor-cell dependency on anti-apoptotic proteins to be highly heterogeneous, with primary MM cells at diagnosis being dependent on MCL-1 or BCL-2, or co-dependent on either BCL-2/MCL-1 or BCL-XL/MCL-1." (PMID 33806619, 2021). "In contrast to the indifference of these tumour cell lines to MCL-1 deletion or inhibition in 2D adherent culture, there was a strong effect in 3D-tumoursphere culture." (PMID 33785871, 2021). "Here, we show inhibition of MCL-1 is sufficient to sensitize SS cell lines to venetoclax in vitro, and, critically, the MCL-1 inhibitor S63845 and venetoclax synergize to induce tumor regression in vivo." (PMID 34065859, 2021). "Echoing our observations made from in vitro treatment, ETC-168 treatment strongly inhibited p-4E in tumor grafts, while S63845 treatment stabilized MCL1." (PMID 33564073, 2021). "These inhibitors suppressed the expression of several genes like Sox2, Sox9, and Mcl1 that promote tumor growth, facilitating growth arrest." (PMID 34359807, 2021). "Some miRNAs display tumor suppressor effects, such as miR-29b, which inhibited the expression of antiapoptotic genes Mcl-1 and Bcl-2, and promoted spontaneous apoptosis of tumor cells." (PMID 34084160, 2021). "MCL1 has also been shown to promote tumor invasiveness via interaction with Cofilin 1, a cytoskeletal remodeling protein, and phosphorylated SRC." (PMID 34469478, 2021). "Tumor suppressor miR-101 that targets MCL-1, a protein belonging to the Bcl-2 family that inhibits apoptosis, inhibits migration, invasion, and EMT in vitro and tumor growth in vivo, and influences patient survival." (PMID 34298609, 2021). "In contrast to its critical role in MMTV-PyMT tumour growth in vivo, we were intrigued by the dispensability of Mcl1 for tumour cell line growth in 2D monolayers in vitro where cell viability was jointly maintained by MCL-1 and BCL-XL." (PMID 33785871, 2021). "MCL1 mRNA and protein expression was found to be increased under insulin treatment in human granulosa-like tumor cells." (PMID 34413875, 2021). "In particular, we demonstrate for the first time that inhibiting MCL-1 function markedly represses PEL-induced tumor growth in xenograft models." (PMID 33471866, 2021). "The NOXA/Mcl-1 axis has been reported to contribute to chemotherapeutically induced apoptosis In many types of tumour cells." (PMID 33557839, 2021).
tumor (continued). "The pro-survival proteins BCL-XL and MCL-1 were obvious candidates as factors enabling this sustained tumour growth as they are expressed at several stages of B lymphopoiesis and are critical to the survival of B lymphoid progenitors and/or precursors." (PMID 33799592, 2021). "Following orthologous transplant of Bax/Bak CRISPR/Cas9 edited MMTV-PyMT cells into WT recipients, tumours were allowed to grow to 5 mm diameter before treatment with MCL-1 inhibitor S63845 or vehicle control." (PMID 33785871, 2021). "Several drugs already used in chemotherapy to suppress tumor growth, including sorafenib, dovitinib and the Mcl-1 inhibitor SC-2001, exert their antitumor effects by enhancing the phosphatase activity of Shp1 on the transcriptional factor STAT3." (PMID 34088320, 2021). "In the present study, we used hepatocyte-specific Mcl-1 knockout mice to evaluate the effect of hepatocyte apoptosis on tumor formation." (PMID 33564095, 2021). "Our results revealed the effect of the novel circMTO1/miR-320b/MCL1 axis in human granulosa-like tumor cells." (PMID 34413875, 2021). "In all cases, CDK9 inhibition leads to the suppression of tumour formation and induces apoptosis via reduction of MCL-1 expression." (PMID 34581776, 2021). "In this study, we investigated possible mechanisms of the acquired resistance of tumor cells to Mcl-1 inhibition." (PMID 35008345, 2021). "In summary, LiCl prevents xenograft tumour growth in mice, and the NOXA/Mcl-1 axis is associated with this effect." (PMID 33557839, 2021). "In vitro and in vivo studies demonstrates that APG-3526 (IC50 = 7 nM) and AS00491 have high affinity for MCL-1 and anti-tumor proliferative capacity." (PMID 33883020, 2021). "Splitting tumours into MCL1-low and MCL1-high groups confirmed that these stemness markers have elevated expression in MCL1-high tumours, which were also significantly enriched for ER-negative tumours." (PMID 33785871, 2021). "In turn, the combination with chemotherapy or ionizing radiation can increase sensitivity to BCL‐2 inhibitors in preclinical tumor cell lines and patient samples by a reduction in MCL‐1 levels." (PMID 33347715, 2021). "CircMTO1 promoted MCL1 expression in human granulosa-like tumor cells and was reversed by the miR-320b mimic." (PMID 34413875, 2021). "FBXW7 reactivation reduced Mcl-1 expression, in turn, increasing the tumor metastatic, invasive, and drug-resistant capacities of lung cancer by depredating specific substrates." (PMID 33676554, 2021). "The striking impact of perturbing MCL-1 dependency on tumor development underscores the need of tumor cells to sustain MCL-1 expression and stability." (PMID 33308268, 2020). "MCL-1 is a member of the anti-apoptotic BCL2 family that is over-expressed in many tumor types and protects tumor cells from invasion 54,55." (PMID 32754285, 2020). "Here, we show that hyperosmotic stress in the tumor environment abrogates dual BCL-XL/MCL-1 protection." (PMID 32312973, 2020). "The IB data revealed that treatment with either Formo or osimertinib decreased the protein level of p-EGFR, p-Akt, and Mcl-1 in xenograft tumor tissues." (PMID 32276600, 2020). "The decreases in tumor expression of Bcl-2 and Mcl-1 after DT2216 treatment were likely due to the activation of caspase-3 and induction of MyLa cell apoptosis." (PMID 32677976, 2020). "In the past, PE-based immunotoxins against different tumor entities were shown to downregulate Mcl-1." (PMID 32580291, 2020). "It was previously observed that the expression of anti-apoptotic proteins including Mcl-1 increases in tumor cells." (PMID 32526993, 2020). "The in vivo tumor growth assay showed that FGD5-AS1 promoted OC tumorigenesis by regulating miR-153-3p/MCL1 axis." (PMID 32675387, 2020). "Of the pro-survival proteins, BCL-XL was strongly expressed in all the MPM cell lines at levels relatively higher than most other tumour cell lines, whilst MCL-1 levels were consistent with the others." (PMID 33298868, 2020).
tumor (continued). "We aim to raise the awareness about the heterogeneous role of MCL-1 as drug target between, but also within tumor entities and to highlight the importance of rationale treatment decisions on a case by case basis." (PMID 33308268, 2020). "In 12/46 (26%) adenocarcinomas, MCL-1 gains appeared subclonally on the branches of the tumour’s phylogenetic trees (e.g. CRUK001)." (PMID 32913197, 2020). "Next, we systematically verified that the shift in the Mcl-1 splicing pattern from Mcl-1L to Mcl-1S induced significant apoptosis, consequently suppressing tumor viability and proliferation in vitro and in vivo." (PMID 33052877, 2020). "For example, BCL2 selective inhibitor ABT-199 has shown high efficacy in the treatment of chronic lymphocytic leukemia (CLL), but it cannot induce apoptosis in certain tumor cell lines with MCL1 amplification." (PMID 33126914, 2020). "This is the first study reporting that the anti-apoptotic MCL-1 protein stability is regulated by the deubiquitinase USP7 in tumor cells (arsenic and BaP co-exposure-transformed cells)." (PMID 32802178, 2020). "Analysis of LUAD samples revealed MCL-1 copy number gains in 46/61 (75%) tumours, of which 10/46 (22%) were high-level." (PMID 32913197, 2020). "To analyse the impact of Mcl-1 deletion on tumour development, we quantified the number of lesions in all the experimental groups." (PMID 32913197, 2020). "Here, SCFFbw targets MCL-1 for destruction in a GSK3β dependent manner and is involved in drug resistance and tumor formation." (PMID 33308268, 2020). "RMSX1 in vivo single agent treatment with vincristine or the MCL-1 inhibitor S63845 merely delayed tumor growth after 21 days." (PMID 32801295, 2020). "Similar results were detected in LUSC tumours, 19/32 (59%) tumours showed MCL-1 gains and 1/19 (5%) was classified as a high-level gain." (PMID 32913197, 2020). "The in vivo xenograft model showed that overexpression of Mcl-1 5KR mutant reduced the anti-tumor efficacy of deguelin." (PMID 32081857, 2020). "As previously observed in a set of human biopsies from control, HCC, and surrounding non-tumorous tissue, BCL-xL mRNA expression was increased in some HCC samples, while MCL-1 reduction was general in all tumor tissues." (PMID 32024199, 2020). "Overall, this study demonstrated that Formo acts as an inhibitor for the EGFR-Akt axis, and promotes FBW7-mediated Mcl-1 ubiquitination is required for the anti-tumor activity of Formo both in vitro and in vivo." (PMID 32276600, 2020). "This is an important finding, since Mcl‐1 expression is related to tumour recurrence and reduced survival rates in CRC patients." (PMID 32352219, 2020). "CDK9 inhibition represents a therapeutically tractable approach for reducing the expression of short‐lived survival factors such as MCL‐1 and subsequently driving apoptosis in tumor cells that depend upon these factors for survival." (PMID 35847704, 2020). "Apart from the genetic inactivation of E3 ligase components, tumor cells use dynamic processes that interfere with the proteasomal degradation of MCL-1." (PMID 33308268, 2020). "The oral administration of KCP10043F decreased tumor growth in an A549 xenograft mouse model, as associated with the reduced phosphorylated STAT3, survivin, Mcl-1, and Bcl-2 expression and increased TUNEL staining and PARP cleavage in tumor tissues." (PMID 32150979, 2020). "Gains of MCL-1 were predominantly clonal, occurring on the trunk of each tumour’s phylogenetic tree." (PMID 32913197, 2020). "The effects of each macrophage phenotype on MCL-1 protein expression were then examined in parallel cell lysates and tumor lysates." (PMID 32444799, 2020).